TGFBI (transforming growth factor beta induced)
Diseases named in the same sentence as TGFBI in open-access papers (continued):
Sharing a sentence is not in itself a finding about the gene and the disease.
ovarian carcinoma (continued). "Both TGFBI and periostin have been implicated in ovarian cancer." (PMID 22640878, 2012). "In addition, loss of TGFBI can induce resistance to chemotherapeutic agent paclitaxel in ovarian cancer cells, while human tumor cells with over-expressed levels of TGFBI showed an increased sensitivity to etoposide, paclitaxel, cisplatin and gemcitabine." (PMID 23077482, 2012). "Our results showed that there were different patterns of mythylation according to the histology and the tumor grade, and revealed that hypermethylation of TGFBI in ovarian cancer might be associated with unfavourable prognosis." (PMID 22248469, 2012). "Moreover, TGFBI could promote metastasis by increasing migration and invasion of ovarian cancer cells via EMT induction, which might be associated with the activation of integrin αvβ3-PI3K-Akt signaling pathway." (PMID 38395907, 2024). "Western blot analysis also confirmed that TGFBI KO ovarian cancer cells had significantly decrease levels of pPI3K and pAkt compared with control cells, while the expressions of pPI3K and pAkt were significantly increased in TGFBI over-expression cells." (PMID 38395907, 2024). "In summary, we screened out TGFBI gene in platelet-treated ovarian cancer cells through combination of our private microarray results with GEO data, and verified its prognostic value in ovarian cancer using cohorts from TCGA and tissue microarray." (PMID 38395907, 2024). "The invasive assays showed that the numbers of ovarian cancer cells that passed through the Transwell membranes were significantly decreased in the TGFBI KO groups compared to the control groups." (PMID 38395907, 2024). "As a result, we found out an adverse prognostic impact of the novel gene TGFBI on the survival of ovarian cancer patients." (PMID 38395907, 2024). "Functionally, TGFBI affected the migration and invasion of ovarian cancer cells by regulation of epithelial mesenchymal transition (EMT) markers (CDH1 and CDH2) and extracellular matrix (ECM) degradation proteins (MMP-2)." (PMID 38395907, 2024). "Tissue microarray results showed that TGFBI was an independent factor for ovarian cancer, and TGFBI expression predict poor prognosis." (PMID 38395907, 2024). "TGFBI was upregulated in cisplatin-sensitive and resistant ovarian cancer cells in a cisplatin time-dependent manner." (PMID 38365849, 2024). "In accordance with previous results, our in vitro and in vivo assays have demonstrated that TGFBI expression had impact not only on migratory and invasive capabilities of ovarian cancer cells, but also peritoneal metastatic colonization." (PMID 38395907, 2024). "In our assay, we have demonstrated that TGFBI activated PI3K-AKT pathway in ovarian cancer cells by combining with integrin αvβ3 using molecular docking and inhibitors." (PMID 38395907, 2024). "TGFBI is lowly expressed in breast cancer, ovarian cancer, and lung cancer, but highly expressed in clear cell renal cancer and colorectal cancer." (PMID 38245723, 2024). "Unbiased proteomics analysis of TGFBI KO ovarian cancer cells and control ones identified differential expression of multiple pathways." (PMID 38395907, 2024). "It has been reported in the literature that treatment of orthotopic mouse ovarian cancer tumors with an anti-TGFBI antibody reduced peritoneal tumor size, increased tumor monocytes, and activated β3-expressing unconventional T cells." (PMID 38166541, 2024). "Further analysis showed that there were also significant declines in the numbers and total weights of metastatic lesions in mice injected with TGFBI KO cells, which suggested that TGFBI affected ovarian cancer metastasis." (PMID 38395907, 2024). "In ovarian cancer, β3 integrin, against β1 integrin and syndecan-1, facilitates cell adhesion to TGFBI and induces migration and paclitaxel resistance." (PMID 36906534, 2023). "TGFBI produced by macrophages can conduce to suppress the immune microenvironment of ovarian cancer." (PMID 35756990, 2022).
ovarian carcinoma (continued). "High expression of TGFBI predicts poor prognosis in patients with colorectal and ovarian cancer, while it also promotes breast cancer metastasis." (PMID 35422813, 2022). "We also examined the protein expression of TGFβ (gene TGFB1), a protein that induces TGFBI and is implicated in EMT in ovarian cancer." (PMID 36463238, 2022). "TGFBI (transforming growth factor-beta-induced protein) is an ECM secretory protein with dual function in ovarian cancer." (PMID 33921897, 2021). "It has been suggested that TGFBI plays a dual role in ovarian cancer and can act both as a tumor suppressor or tumor promoter depending on the tumor microenvironment." (PMID 33912443, 2021). "Elevated levels of TGFBI have been associated, in common with its paralogue POSTN, with poor survival in patients with ovarian cancer." (PMID 34561272, 2021). "In most papers, the expression of TGFBI is silenced in ovarian cancer tissue and cell lines, and it correlates with PAC resistance." (PMID 33921897, 2021). "Previously, we reported an increased expression of TGFBI in three TOP-resistant ovarian cancer cell lines." (PMID 33921897, 2021). "Analysis of ECM changes during neoplastic transformation reveals a role for TGFBI secreted by macrophages in immunosuppression in early ovarian cancer." (PMID 34561272, 2021). "Previously, we observed an upregulation of TGFBI in three TOP-resistant ovarian cancer cell lines and suggested its role as one of the TOP-resistance genes." (PMID 33921897, 2021). "Recently, we also described TGFBI as a gene related to TOP resistance in three different ovarian cancer cell lines." (PMID 32283808, 2020). "In ovarian cancer and esophageal squamous cell carcinoma, a dual function of TGFBI depending on its cellular origin has been discussed." (PMID 32312959, 2020). "Low expression of TGFBI in ovarian cancer cells promoted tumor growth, whereas its high expression in peritoneal cells facilitated the migration of cancer cells." (PMID 31598162, 2019). "TGFBI functions as a tumor suppressor has been found in many tumors, as in human lung carcinoma, ovarian carcinoma and breast carcinoma." (PMID 29609638, 2018). "Immunohistochemical analysis of selected (EPHA7, IFI-16, SPP1 and TGFBI) proteins was tested in ovarian cancer patients." (PMID 28611294, 2017). "The expression of EPHA7, IFI16, SPP1 and TGFBI was confirmed at protein level in analyzed ovarian cancer patients.." (PMID 28611294, 2017). "Nearly all of the reports indicated that the expression level of TGFBI in ovarian cancers and ovarian cancer cell lines was decreased via promoter methylation." (PMID 28611294, 2017). "We have previously shown that the secreted ECM protein transforming growth factor beta induced (TGFBI) sensitizes ovarian cancer cells to the mitotic inhibitor paclitaxel by regulating microtubule stability via integrin-mediated FAK and RhoA activation." (PMID 27622658, 2016). "Recent identification of TGFBI’s role in chemotherapeutic response and its possible dysregulation during ovarian cancer progression led to our investigation of its organization within the extracellular compartment." (PMID 27622658, 2016). "Our previous work has identified expression of TGFBI to be necessary for sensitizing ovarian cancer cells to paclitaxel-induced cell death." (PMID 27622658, 2016). "TGFBI has been shown to sensitize ovarian cancer cells to the cytotoxic effects of paclitaxel via an integrin receptor-mediated mechanism that modulates microtubule stability." (PMID 27622658, 2016). "Recent evidence indicates that TGFBI influences ovarian cancer response to paclitaxel by stabilizing the microtubule cytoskeleton through an integrin-dependent signalling pathway." (PMID 27622658, 2016). "TGFBI promoter hypermethylation, which suppresses TGFΒΙ expression, is found in ovarian carcinoma specimens." (PMID 25889002, 2015).
ovarian carcinoma (continued). "In our results, TGFBI methylation was detected in 29/40 (72.5%) of ovarian cancer and 1/10 (10%) of benign ovarian tumors." (PMID 22248469, 2012). "We determined the frequency of TGFBI methylation in 40 primary ovarian cancer samples, 10 benign ovarian tumors and 10 normal ovarian tissues by MSP." (PMID 22248469, 2012). "Since this contrasts to the function of TGFBI in ovarian cancer, there lacks a clear understanding of the differential signaling that occurs upon engagement of the cell surface with various ECM components." (PMID 22640878, 2012). "The methylation status of TGFBI was examined in ovarian cancer and control groups by methylation-specific PCR (MSP) and bisulfite sequencing PCR (BSP)." (PMID 22248469, 2012). "The expression of TGFBI mRNA was examined in all the 6 ovarian cancer cell lines by qRT-PCR before and after treating with 5-aza-dc." (PMID 22248469, 2012). "The purpose of this study is to determine the methylation status of Transforming growth factor-beta-inducible gene-h3 (TGFBI) and its correlation with paclitaxel chemoresistance in ovarian cancer." (PMID 22248469, 2012). "Loss of βig-H3 expression has been described in several cancers including ovarian cancer and promoter hypermethylation has been identified as an important mechanism for the silencing of the TGFBI gene." (PMID 22949874, 2012). "For example, it has been suggested that TGFBI increases the metastatic ability of colon and an ovarian cancer cell lines In addition, TGFBI has been shown to be over-expressed in pancreatic cancer, renal cell carcinoma and glioblastoma." (PMID 22695319, 2012). "In conclusion, our study indicated that promoter hypermethylation of TGFBI is a frequent event in ovarian cancer." (PMID 22248469, 2012). "TGFBI mRNA expression was detected in all the normal ovarian tissues (10/10) and in most of the unmethylated ovarian cancer tissues (10/11)." (PMID 22248469, 2012). "In ovarian cancer cells, which express both the ß1 and ß3 integrin subunits, TGFBI preferentially interacts with cells through an αvß3 integrin-mediated mechanism." (PMID 22640878, 2012). "Periostin is secreted by ovarian cancer, similar to TGFBI, and promotes integrin-mediated cell motility." (PMID 22640878, 2012). "The data demonstrated that the difference of TGFBI methylation frequency among ovarian cancers, benign ovarian tumors and normal ovarian tissues was statistically significant (P < 0.001)." (PMID 22248469, 2012). "After repeated experiments, our results showed that the TGFBI is frequently methylated in ovarian cancer." (PMID 22248469, 2012). "It has been previously shown that αvβ3 integrin mediates paclitaxel sensitivity of ovarian cancer cells that transiently expressed TGFBI." (PMID 20509890, 2010). "In this regard, expression of the ECM protein TGFBI has recently been reported to influence paclitaxel sensitivity of ovarian carcinoma cells." (PMID 18460215, 2008). "Therefore, we tested the effects of TGFBI on metastasis in murine peritoneal dissemination model using TGFBI KO SKOV-3 ovarian cancer cells." (PMID 38395907, 2024). "Similarly, we observed that silencing TGFBI in SKOV-3 and Caov-3 cells resulted in increased expression of CDH1 (E-cadherin) and decreased CDH2 (N-cadherin), suggesting that TGFBI affected the metastatic capabilities of ovarian cancer cells via EMT reprogram." (PMID 38395907, 2024). "Univariate analysis indicated that TGFBI was a prognostic predictor for ovarian cancer patients (HR = 1.16, 95% CI: 1.04–1.29, p < 0.01), and it was still proved to be an independent adverse factor in the multivariate analysis (HR = 1.35, 95% CI: 1.15–1.58, p < 0.01)." (PMID 38395907, 2024). "Moreover, TGFBI was highly expressed in cisplatin-resistant ovarian cancer cells than sensitive ovarian cancer cells." (PMID 38365849, 2024).
ovarian carcinoma (continued). "Furthermore, TGFBI knockdown leads to SKOV-3 cells being resistant to paclitaxel, and TGFBI was considered a marker for paclitaxel-resistant ovarian cancer cell line." (PMID 38968283, 2024). "Finally, we identified TGFBI gene as the potential prognostic factor for ovarian cancer through a series of bioinformatics analysis." (PMID 38395907, 2024). "Considering its biological function of metastatic promotion, we speculated that TGFBI-induced EMT in the ovarian cancer cells might link with its ability to activate the PI3K-AKT signaling pathway." (PMID 38395907, 2024). "TGFBI was significantly higher expressed in the platelet-treated ovarian cancer cells." (PMID 38395907, 2024). "TGFBI could promote metastasis in ovarian cancer by EMT induction and ECM remodeling, which might be associated with the activation of integrin αvβ3-PI3K-Akt signaling pathway." (PMID 38395907, 2024). "Finally, more clinical research should be carried out to verify the prognostic effect of TGFBI on ovarian cancer." (PMID 38395907, 2024). "Moreover, the mRNA level of TGFBI was significantly higher in ovarian cancer tissues than in normal tissues, and the higher level of TGFBI, the poorer prognosis of ovarian cancer patients." (PMID 38365849, 2024). "However, the concrete functions of TGFBI in molecular regulation for ovarian cancer metastasis remained unclear." (PMID 38395907, 2024). "Functionally, we suggested that TGFBI affect metastatic potentials of ovarian cancer cells by inducing EMT and remodeling ECM, which might be associated with the activation of integrin αvβ3-PI3K-Akt signaling pathway." (PMID 38395907, 2024). "Moreover, TGFBI was selected to further explore its specific mechanism in hypoxia and ovarian cancer progression and chemotherapy." (PMID 38365849, 2024). "We found out TGFBI as a novel prognostic indicator for ovarian cancer patients." (PMID 38395907, 2024). "Hence, the expression level of TGFBI was expected to be a candidate biomarker for the construction of ovarian cancer prognostic models." (PMID 38395907, 2024). "Furthermore, TGFB1 was proposed to contribute to immunosuppression and disease progression in ovarian cancer via the induction of TGFBI in macrophages." (PMID 37370765, 2023). "This promoter hypermethylation of TGFBI correlates with paclitaxel resistance in ovarian cancer." (PMID 36463238, 2022). "TGFBI has been proved to be related with paclitaxel-resistance in ovarian cancer, which might be a potential therapeutic target for the enhancement of responses to chemotherapy in ovarian cancer patients." (PMID 33987033, 2021). "It is speculated that high expressed TGFBI may be related to the survival benefit for ovarian cancer patients on chemotherapy treatment." (PMID 34888242, 2021). "In ovarian cancer, TGFBI can enhance cell adhesion, motility and invasion." (PMID 34686725, 2021). "Contrary to the hypothesis that those upregulated candidate genes might be a survival benefit for ovarian cancer, high IGFBP4 and TGFBI gene expressions were associated with decreased OS rather than prolonged survival." (PMID 34888242, 2021). "TGFBI increased the metastatic potential of ovarian cancer cells, and TGFBI may be a potential therapeutic target against ovarian cancer." (PMID 33912443, 2021). "TGFBI level got down-regulated due to promoter hypermethylation in ovarian carcinoma tissues." (PMID 33912443, 2021). "On the other hand, TGFBI promoted invasion and metastasis of ovarian cancer." (PMID 33921897, 2021). "As suggested for ovarian cancer, TGFBI might have a similar role in the development of endometriotic peritoneal implants." (PMID 34686725, 2021). "In addition, mechanistic studies have shown that TGFBI is strongly associated with chemotherapy in NSCLC and ovarian cancer." (PMID 33614494, 2020). "Our results also indicate that TGFBI is expressed in ovarian cancer patients." (PMID 28611294, 2017).
ovarian carcinoma (continued). "However, we found much data concerning the expression of TGFBI in ovarian cancer and in Pac-resistant cells." (PMID 28611294, 2017). "Furthermore, our data suggests that the ability of SPARC to regulate extracellular TGFBI influences both ovarian cancer motility and response to the chemotherapeutic agent, paclitaxel." (PMID 27622658, 2016). "In addition, TGFBI has been shown to be dysregulated in a variety of cancers, including its downregulation in ovarian cancer." (PMID 27622658, 2016). "In addition, various ECM components, including collagen VI, TGFBI, and decorin are associated with an ECM signature in ovarian cancer that has been implicated in poor prognosis and drug resistance." (PMID 27622658, 2016). "Recombinant TGFBI promotes ovarian carcinoma cell mobility and invasiveness." (PMID 25889002, 2015). "In addition, extracellular TGFBI increases the motility and invasiveness of ovarian cancer cells and stimulates a peritoneal cell interaction." (PMID 22640878, 2012). "In this study, we first detected the methylation status of the 5' CpG island of TGFBI in different ovarian tissues using MSP and BSP in order to determine whether TGFBI inactivation by DNA methylation is characteristic of human ovarian cancer." (PMID 22248469, 2012). "Therefore, although ovarian cancer cells have the ability to adhere to both periostin and TGFBI, they likely utilize distinct mechanisms." (PMID 22640878, 2012). "We first compared the functions of TGFBI and periostin on ovarian cancer cells." (PMID 22640878, 2012). "TGFBI might be a potential therapeutic target for the enhancement of responses to chemotherapy in ovarian cancer patients." (PMID 22248469, 2012). "We further measured TGFBI mRNA and protein levels by RT-PCR and IHC in ovarian cancer tissues." (PMID 22248469, 2012). "To examine whether TGFBI methylation results in the suppression of TGFBI expression, we examined TGFBI mRNA expression by qRT-PCR in 40 ovarian cancer tissues and 10 normal ovarian tissues." (PMID 22248469, 2012). "More specifically, recent evidence suggests that TGFBI is dysregulated in ovarian cancer and its expression level may influence cancer response to the chemotherapeutic agent paclitaxel." (PMID 22640878, 2012). "The TGFBI expression was increased with the increase of cisplatin concentration gradient, and downregulation of TGFBI could impair the chemoresistance of cisplatin-resistant ovarian cancer cells." (PMID 38365849, 2024). "Moreover, we found that Cyclo (-RGDyK) could further decrease the migration and invasion of TGFBI KO ovarian cancer cells." (PMID 38395907, 2024). "Furthermore, we found that TGFBI may function as a key regulator in chemoresistance of ovarian cancer mainly through activating HR DNA repair and NHEJ DNA repair; also, TGFBI activate PI3K/Akt pathway to inhibit cell apoptosis and facilitate chemoresistance." (PMID 38365849, 2024). "However, because TGFBI was expressed in all of the Top-resistant ovarian cancer cell lines, its expression might be a marker of Top-resistance in ovarian cancer." (PMID 28611294, 2017). "Therefore, a better understanding of this epigenetic mechanism of TGFBI in ovarian cancer could facilitate the generation of new drugs that re-sensitize tumor cells to paclitaxel." (PMID 22248469, 2012). "Therefore, we tested whether the ERGDEL peptide derived from TGFBI was capable of competitively inhibiting adhesion of ovarian cancer cells to fibronectin and rTGFBI." (PMID 22640878, 2012). "Therefore, evaluating the mechanism of TGFBI and periostin function in ovarian cancer cells may shed light on their relationship and function during ovarian carcinogenesis." (PMID 22640878, 2012). "Therefore, different ECM components use distinct signaling mechanisms in ovarian cancer cells and in particular, TGFBI preferentially interacts through a ß3 integrin receptor mediated mechanism to regulate the response of cells to paclitaxel-induced cell death." (PMID 22640878, 2012).